RNU6-626P (RNA, U6 small nuclear 626, pseudogene)
Gene: Small nuclear RNA gene on chromosome 6 (56,945,730 to 56,945,836, forward strand). Ensembl gene ENSG00000200224.
Homologues: Orthologues: chimpanzee U6 (100% identical), macaque U6 (93% identical), guinea pig U6 (79% identical), rat LOC120103197 (79% identical). Paralogues in human: RNU6-393P (83% identical), RNU6-1145P (82% identical), RNU6-16P (82% identical), RNU6-46P (82% identical), RNU6-480P (82% identical), RNU6-1089P (81% identical), RNU6-1209P (81% identical), RNU6-1316P (81% identical), RNU6-20P (81% identical), RNU6-25P (81% identical), RNU6-29P (81% identical), RNU6-38P (81% identical), and 1286 more.